AR (androgen receptor)
Diseases named in the same sentence as AR in open-access papers (continued):
Sharing a sentence is not in itself a finding about the gene and the disease.
prostate carcinoma (continued). "A classic example of gene alteration resulting from AS is the androgen receptor splice variant (AR-V7), which is the best-characterised androgen receptor (AR) splice variant in advanced prostate cancer." (PMID 40282556, 2025). "AR inhibitors are crucial in prostate cancer, where AR expression levels and mutations influence therapeutic outcomes." (PMID 40717128, 2025). "Lineage plasticity, or differentiation change, in prostate cancer is most commonly exemplified by AR pathway loss and switch from a luminal to an alternate differentiation program." (PMID 40454483, 2025). "Aggressive prostate cancer (PCa) variants associated with androgen receptor signaling inhibitor (ARSI) resistance and metastasis remain poorly understood." (PMID 39748059, 2025). "JJ-450 inhibited androgen receptor (AR) and its variant ARv7 to suppress castration-resistant prostate cancer." (PMID 39885614, 2025). "MBC has been linked to the androgen receptor (AR) axis, which has historically been linked to prostate cancer." (PMID 41502531, 2025). "SPOP mutations, which occur in approximately 10% of prostate cancers, seem to have an oncogenic role that is in part related to the impaired degradation of oncoproteins such as AR." (PMID 40075623, 2025). "Since mutations of the AR gene are associated with higher malignancy of prostate cancer, we investigated the mutational status of the AR to address any possible interactions also in glioma." (PMID 41153666, 2025). "Beyond its established role in G1 cell cycle progression, CDK6 has been implicated in the stimulation of AR activity, potentially contributing to prostate cancer development and progression." (PMID 40304827, 2025). "In prostate cancer, the androgen receptor splice variant-7 (AR-V7) shows ligand-independent activation of the receptor, leading to treatment failure under androgen-suppressing medication in patients with advanced prostate cancer." (PMID 40074836, 2025). "(2023) revealed that androgen receptor variants in prostate cancer upregulate SLC7A11 and confer ferroptosis resistance, consistent with our identification of SLC7A11 as a central molecule in resistance regulation." (PMID 40416987, 2025). "In advanced prostate cancer, three main components stand out: circulating tumor DNA (ctDNA), circulating tumor cells (CTCs), and the androgen receptor splice variant AR-V7." (PMID 41374949, 2025). "In cases of advanced prostate cancer, patients develop resistance to standard androgen deprivation therapies (ADTs) due to AR mutations, leading to the continued growth of cancer cells." (PMID 39851497, 2025). "MYBL2 upregulation has also been linked with prostate cancer aggressiveness and resistance to AR targeting and appears to be a key target of the histone demethylase KDM5B58." (PMID 40624104, 2025). "NGS enables a deeper understanding of the prostate cancer genome, revealing mutations in genes like the androgen receptor (AR) and DNA repair pathways." (PMID 40660132, 2025). "Another observation reflecting the intimate association between BRD4, CDK9 and AR in prostate cancer is that cells that have acquired resistance to BRD4 inhibition exhibit adaptive responses to AR and CDK9." (PMID 40163908, 2025). "In a study using mice, surgical castration induced an increase in the expression of circulating miR-125b, while an AR blockade (via bicalutamide) was associated with the rapid release of miR-125b into a cell culture medium of prostate cancer cells." (PMID 40869103, 2025). "Prostate cancer ranks among the most prevalent male malignancies, characterized by deregulated androgen receptor (AR) signaling and DNA repair gene mutations—key molecular hallmarks driving its pathogenesis." (PMID 40331986, 2025). "Cluster 4 comprised hallmark pathways associated with cell proliferation (G2M checkpoint, E2F targets, MYC targets), DNA repair and tumor suppressor loss, and the MetB signature associated with a low AR/high proliferation prostate cancer phenotype." (PMID 39985777, 2025).
prostate carcinoma (continued). "Third, inhibition of HSP27 leads to AR and AR-V7 degradation with associated growth inhibition of treatment-resistant prostate cancer models." (PMID 39787247, 2025). "LCMT1 methylates the C-terminal leucine of PPP2R2A to regulate PP2A substrate specificity and has been implicated in prostate cancer through AR regulation." (PMID 40493189, 2025). "Another H3K4 HDM, KDM5D, is also implicated in androgen receptor signaling and thus prostate cancer." (PMID 40356745, 2025). "These organelles play a crucial role in lipid and redox metabolism, and alterations in their function have been associated with androgen receptor signaling, prostate cancer progression, and therapy resistance." (PMID 40647540, 2025). "AU-15330 is a highly selective degrader targeting SMARCA2 and SMARCA4, which induces a specific loss of chromatin accessibility at enhancers in prostate cancer cells driven by AR and FOXA1." (PMID 40032852, 2025). "Computational studies have also examined PARP7 modulation and its association with androgen receptor signalling in prostate cancer." (PMID 41294806, 2025). "While the abnormal expression and dysregulation of the AR are implicated in the occurrence and progression of malignancies such as prostate cancer, breast cancer, and liver cancer, its specific roles in HNSCC remain to be elucidated." (PMID 40729027, 2025). "AR is a key marker in prostate cancer, characteristic of luminal tumors, and is associated with hormone responsiveness, which supports the different androgen deprivation therapy (ADT) sensitivities." (PMID 40867349, 2025). "GSNO treatment led to a significant reduction in their expression, indicating NO’s ability to counteract ER stress in AR-deficient prostate cancer cells." (PMID 41198652, 2025). "Prostate cancer is a leading cause of cancer-related deaths among men with androgen receptor (AR) signaling playing a pivotal role in its development and progression." (PMID 39858458, 2025). "Mutations in AR can lead to patients with castration‐resistant prostate cancer acquiring resistance to most drugs." (PMID 40599234, 2025). "A hallmark of prostate cancer is its dependence on the androgen signalling axis and the androgen receptor (AR)." (PMID 40163908, 2025). "While different mutations in the androgen receptor have been documented in prostate cancer, particular mutations (such as L702H, W742L/C, H875Y, F877L, and T878A/S) are commonly detected following the development of treatment resistance." (PMID 40356745, 2025). "AR mutations have been extensively studied in prostate cancer; their role in osteosarcoma and other sarcomas is less defined." (PMID 41514647, 2025). "As the roles and nature of specific AR variants have yet to be characterized in HCC as they have been in prostate cancer, this work limited its scope to AR-SVs broadly." (PMID 40805231, 2025). "Prolonged ADT induces decreased androgen receptor (AR) expression and/or AR mutations in prostate cancer cells, with suppression or loss of AR signaling being a central driver of NED." (PMID 41573638, 2025). "The results provide insights into the diverse biochemical characteristics that endow prostate carcinoma with the ability to survive AR-directed therapy and identify features that underlie variation in treatment-resistant phenotypes observed in patients." (PMID 40956611, 2025). "Androgen receptor enhancers are extremely heterogeneous and associated with chromatin remodeling that impacts prostate cancer susceptibility to treatment." (PMID 40406098, 2025). "EBF1, or early B cell factor 1, has been implicated in the development of prostate cancer through its regulation of androgen receptor (AR) signaling and the androgen response." (PMID 39364872, 2025). "We report that a higher Gene Ontology (GO) cellular response to heat gene expression signature in advanced prostate cancer tissue biopsies associates with increased AR signaling and worse overall survival (OS)." (PMID 39787247, 2025).
prostate carcinoma (continued). "The AR is fundamental to the biology of prostate cancer, regulating the expression of genes associated with cell proliferation, differentiation and survival." (PMID 40563466, 2025). "Collectively, these studies emphasize the necessity of profiling AR mutations to guide therapeutic decisions and monitor adaptive responses in both treatment-naïve and castration-resistant prostate cancer patients." (PMID 40297177, 2025). "Many aggressive variants of prostate cancer, such as AR-independent and NEPC subtypes, are often characterized by low serum PSA secretion but rapid progression and poor prognosis." (PMID 40647509, 2025). "A study revealed that the shortening of the AR (N-terminal poly(Q) tract) increases prostate cancer risk by enhancing androgen-dependent transcriptional activity." (PMID 40065228, 2025). "In summary, our study, for the first time, revealed a key cell type mediating germline risk in prostate cancer and uncovered high-confidence loci in promoters of genes involved in AR-mediated regulons." (PMID 41468516, 2025). "Emerging evidence underscores the critical role of androgen receptor (AR) mutations in driving therapeutic resistance in prostate cancer." (PMID 40297177, 2025). "The emergence of constitutively active androgen receptor (AR) splice variant AR‐V7 poses a formidable challenge in treating prostate cancer, as it lacks the ligand binding region targeted by androgen‐deprivation therapies such as enzalutamide and abiraterone." (PMID 39948708, 2025). "In summary, we identify a striking elevation of p300/CBP-catalyzed H2BNTac as a hallmark of prostate cancer, with p300 co-occupancy serving to define hyperactivated AR enhancers." (PMID 41044247, 2025). "Collectively, our integrated analysis suggest that attenuated LKB1 pathway activity is linked with AR independence in human prostate cancers." (PMID 39743630, 2025). "Androgen receptor (AR) signaling is implicated as the main driver mechanism of prostate cancer (PCa)." (PMID 40128585, 2025). "Recent phase 3 clinical trial showed improved radiographic progression-free survival in PTEN-deficient prostate cancers treated with combined Akt and AR inhibition." (PMID 39919177, 2025). "For AR mutation, this gene was not only significantly enriched following prostate cancer progression, but was also associated with prognosis of time to progression." (PMID 41463218, 2025). "Especially, AR is expressed in primary prostate cancer, while it loses its expression or develops variants in CRPC or NEPC." (PMID 39858458, 2025). "In prostate cancer, autophagy has been implicated in resistance to androgen receptor-targeting therapies, including abiraterone and enzalutamide." (PMID 41446858, 2025). "Androgen receptor signaling has been found to affect the expression of PD-L1 in prostate cancer, with AR activation linked to higher PD-L1 levels." (PMID 39859417, 2025). "Although androgen-deprivation therapy can influence these pathways, prostate cancer cells eventually become castration-resistant via various mechanisms that include AR mutations, AR amplification, and aberrant activation of AR." (PMID 40075623, 2025). "CDC6 was considered as the replication licensing factor, which was also associated with epithelial-mesenchymal transition inducing androgen receptor blockade therapeutic resistance in prostate cancer." (PMID 39376555, 2024). "Genetic polymorphisms in the AR gene have long been associated with prostate cancer risk and progression." (PMID 39600743, 2024). "In male carriers, the risk of prostate cancer is higher given that CHEK2 upregulation reduces cell growth whereas its downregulation alters androgen receptor activity." (PMID 38313678, 2024). "Prostate cancer cells express endogenous full‐length AR (AR‐FL), where the emergence of AR splice variants (AR‐Vs) is associated with the therapy‐resistant disease." (PMID 38605607, 2024).
prostate carcinoma (continued). "A further clinical example of where degraders have been used to mitigate resistance mutations is the androgen receptor (AR), an important target in prostate cancer (PC)." (PMID 38607017, 2024). "Recently the role of the filamin A/AR signalling axis was uncovered in prostate cancer associated fibroblasts (pCAFs)." (PMID 38958472, 2024). "We find heterologous responses to the platinum-based drugs that are associated with prostate cancer cell types with different AR status, and we identify Coilin and TDP-43 as prominent platinum-responsive nuclear proteins." (PMID 38218884, 2024). "As increased activity AR is heavily implicated in prostate cancer, the characterisation of filamin A's role in this disease has received much attention." (PMID 38958472, 2024). "Prostate cancer progression is associated with the increasing interplay of ALDH1A1 with androgen receptor (AR) and retinoid receptor (RAR) transcriptional programs." (PMID 38169509, 2024). "Primary osteoporosis has been treated with hormone replacement therapy and selective androgen receptor modulators (SARMs), but long-term use has been associated with increased rates of heart disease, stroke, and breast cancer and prostate cancer." (PMID 38817601, 2024). "Evaluation of fall and fracture risk among men with prostate cancer treated with androgen receptor inhibitors: a systematic review and meta-analysis." (PMID 39356323, 2024). "In prostate cancer (PCa) and other cancers linked to sex hormones, the androgen receptor (AR) plays a pivotal role in tumour progression." (PMID 39624842, 2024). "In prostate cancer, AR splice variants are produced through alternative splicing, where differential processing of AR pre-mRNA removes exons encoding the ligand-binding domain (LBD)." (PMID 39199550, 2024). "Studies in prostate cancer have shown that the AR and YAP (Hippo pathway effector Yes-associated protein (YAP) interact and that their translation and activity are correlated)." (PMID 39769441, 2024). "Lastly, Nrp2-mediated regulation of the androgen receptor (AR), a ligand-dependent nuclear transcription factor, is implicated in prostate cancer progression and resistance to therapy." (PMID 38592275, 2024). "Understanding the intricate interplay between these pathways and the androgen receptor signalling cascade is paramount for developing diagnostic strategies and targeted therapies to implement personalised management for patients with prostate cancer." (PMID 39858418, 2024). "This study aimed to compare the differences between EV DNA and cfDNA in mutation detection and explore the role of plasma androgen receptor (AR) mutations in the prognosis of prostate cancer (PCa)." (PMID 39535155, 2024). "MiR-30c-1-3p has been shown to suppress metastasis of gastrointestinal stromal tumors, and is associated wth prevention of prostate cancer progression by modulating cell proliferation via androgen receptor downstream targets." (PMID 38665804, 2024). "As a ligand-dependent transcription factor, AR regulates genes associated with prostate cancer growth and metastasis." (PMID 39770110, 2024). "Neuroendocrine prostate cancer (NEPC) is a lethal subset of prostate cancer which is characterized by neuroendocrine differentiation and loss of androgen receptor (AR) signaling." (PMID 38745318, 2024). "Nevertheless, the underlying molecular apoptotic mechanisms of Astragalus membranaceus are not fully understood in association with HSP27 and the AR in prostate cancer." (PMID 38474045, 2024). "TAF1 is implicated in prostate cancer pathogenesis owing to its regulation of the androgen receptor (AR), which represents a sterol receptor that requires multiple components of the transcription machinery to regulate its target genes in the prostate." (PMID 39323550, 2024). "The early recognition of the role of glucocorticoids in prostate cancer stemmed from studies involving ligand-binding domain mutated AR." (PMID 39027480, 2024).
prostate carcinoma (continued). "Neuroendocrine prostate cancer (NEPC), a lethal subset of prostate cancer (PCa), is characterized by loss of AR signaling and resistance to AR-targeted therapy." (PMID 39014441, 2024). "Negative regulation of prostate cancer growth and invasion by stromal AR have also been reported, and Ets Variant Gene 1 (ETV1) was identified as a novel androgen-regulated gene." (PMID 39459070, 2024). "The hallmark of prostate cancer progression is the androgen receptor (AR) signaling pathway, which is mainly responsible for prostate cell survival, proliferation, and resistance to treatment." (PMID 38201308, 2024). "Since prostate cancer is a hormone‐dependent tumour, the occurrence and progression of the disease are closely linked to the androgen receptor (AR) signalling pathway." (PMID 38736108, 2024). "Targeted treatments utilizing AR inhibitors, castration, and other endocrine therapies have successfully reduced the risk of death in patients with advanced prostate cancer by approximately 30–40%3,5." (PMID 38182647, 2024). "The androgen receptor (AR) drives all stages of prostate cancer by various mechanisms, including AR gene mutation, overexpression, epigenetic modification, altered levels of co‐regulators, or the development of new AR variants." (PMID 38605607, 2024). "Over 50% of patients with castration-resistant prostate cancer had numerous AR splice variants, with 1 out of 6 cancer cells expressing various AR splice variants." (PMID 38607014, 2024). "For example, in PTEN-deficient prostate cancer, androgen-bound AR leads to an increase of Akt phosphorylation that in turn regulates AR transcriptional activity and expression." (PMID 39469929, 2024). "Chronic administration of VPA, for instance, in prostate cancer cell lines can cause significant cellular toxicity and alterations in androgen receptor levels at much lower doses than observed during acute administration." (PMID 39093886, 2024). "In prostate cancer, GR signaling has been implicated as a mechanism of resistance to androgen receptor pathway inhibitors (ARPI), such as enzalutamide and apalutamide." (PMID 39177285, 2024). "HSP27/AR signaling is closely associated with prostate cancer progression and resistance to androgen ablation." (PMID 38474045, 2024). "In this paper, the apoptotic mechanism of a water extract from the dried root of Astragalus membranaceus (WAM) was investigated in prostate cancer cells in association with heat shock protein 27 (HSP27)/androgen receptor (AR) signaling." (PMID 38474045, 2024). "Androgen receptor (AR) and its constitutively active splice variant, AR Variant 7 (AR-V7), regulate genes essential for the development and progression of prostate cancer." (PMID 38410785, 2024). "By correlating cistrome activity with genotype, CWAS calculates peak‐trait associations, as demonstrated in prostate cancer studies, where 74 significant AR peaks and 199 H3K27ac peaks were identified." (PMID 39099406, 2024). "AR splice variants promote osteoblastic bone lesions of prostate cancer by transcriptionally activating a specific metastasis program that is distinct from the full-length AR activity." (PMID 38687617, 2024). "The Simon Linder team at the Netherlands Research Institute carried out a comprehensive polynomial analysis of tissues isolated after 3 months of AR-targeted enzalutamide monotherapy in patients with high-risk prostate cancer." (PMID 39011396, 2024).